MEN1 (menin 1)
Diseases named in the same sentence as MEN1 in open-access papers (continued):
Sharing a sentence is not in itself a finding about the gene and the disease.
liver cirrhosis (1 paper, 2025). "An analysis of the clinical liver cirrhosis database revealed that the mRNA expression of Men1 and Setd2 in cirrhotic livers was significantly lower than that in normal livers, whereas the expression of Kmt2a was slightly greater." (PMID 40651612, 2025).
liver steatosis (1 paper, 2023). "Hepatocyte-specific deletion of Men1 induces liver steatosis in aging mice." (PMID 37740216, 2023).
lobular neoplasia (1 paper, 2024). A spectrum of non-invasive neoplastic lesions that arise from the terminal ductal lobular units of the breast. "It is worth mentioning that our results suggest that MEN1 could also be relevant in PDAC neuroendocrine as previously reported, but is also relevant in PDAC because, in this study, all cases are patients with ductal and lobular neoplasias." (PMID 38397997, 2024).
lymphopenia (1 paper, 2024). Reduction in the number of lymphocytes. "Perhaps USP8 and MEN1 are the key genes between cortisol regulation and lymphopenia, which needs further confirmation." (PMID 38376054, 2024).
malignant adrenocortical tumors (1 paper, 2023). "Even though loss of heterozygosity at the MEN1 locus on chromosome 11q13 can be frequently documented in ACC, somatic mutation of the MEN1 gene in sporadic benign or malignant adrenocortical tumors appears to be rare." (PMID 37409236, 2023).
malignant peritoneal mesothelioma (1 paper, 2025). An aggressive malignant mesothelioma that arises from the peritoneum. "Recently, pediatric malignant peritoneal mesothelioma cases have been genetically studied, with alterations observed in ALK, EWSR1, FUS1, YY1, or in AURKA, AURKC, HLA-1B, ZNF-217, OR5F1, and MEN1 genes, but not in BAP1." (PMID 40725095, 2025).
malnutrition (1 paper, 2024). Inadequate nutrition resulting from poor diet, malabsorption, or abnormal nutrient distribution. "Due to the high probability of malnutrition, MEN1 patients should be advised to undergo periodic screening to define the level of risk of nutritional deficiency." (PMID 38892509, 2024). "This should be part of the routine care of every MEN1 patient, as malnutrition has substantial negative consequences, including increased mortality, poorer quality of life and increased healthcare costs." (PMID 38892509, 2024). "Another important aspect to be considered is the management of MEN1 patients with multiple GEP-NETs, who have undergone major resections of the duodenum and/or the pancreas, with consequent malabsorption and malnutrition, worsening the general clinical picture and the quality of life." (PMID 38892509, 2024).
Miscarriage (1 paper, 2022). A pregnancy that ends at a stage in which the fetus is incapable of surviving on its own, defined as the spontaneous loss of a fetus before the 22th week of pregnancy. "Collectively, these results demonstrated that uterine-specific deletion of Men1 disturbed the progression of decidualization and ultimately resulted in embryo resorption and miscarriage at mid-gestation." (PMID 35194044, 2022).
myelolipoma (1 paper, 2023). "Previously reported cases of MEN1-associated adrenal myelolipoma did not exhibit LOH, suggesting that menin is not a contributing factor to myelolipoma." (PMID 37867522, 2023).
nodular goiter (1 paper, 2021). Goiter characterized by discrete tissue mass(es) that may or may not produce thyroid hormones. "In the earlier studies, nodular goiters were linked to MEN1, while the more recent ones show that the rate of concurrence of a thyroid incidentaloma is comparable in MEN1-positive and -negative patients." (PMID 33807230, 2021).
oral cancers (1 paper, 2020). "Intriguingly, causes of death in one third of MEN1 patients do not involve MEN1-related causes, such as cardiovascular disease and neoplasms arising from other sites like colorectal, renal, lung, breast, and oral cancers." (PMID 33312161, 2020).
pituitary (1 paper, 2016). "The antiproliferative and proapoptotic actions of pasireotide on the pancreatic and pituitary NETs of Men1+/− mice, which included reduced pituitary NET size, were associated with higher survival in the pasireotide-treated Men1+/− mice." (PMID 26990064, 2016). "In summary, pasireotide treatment in Men1+/− mice with pancreatic and pituitary NETs was associated with reduced proliferation and increased apoptosis of NETs which resulted in approximately 20% improvement in survival." (PMID 26990064, 2016). "Our results show that pasireotide, a multireceptor-targeted SA with high affinity for SSTR1, 2, 3, and 5 is effective in reducing proliferation and increasing apoptosis of pancreatic and pituitary NETs that develop in a mouse model for MEN1." (PMID 26990064, 2016). "Thus, at 21 months of age 31.3% of PBS-treated Men1+/− mice (10/32) had pituitary NETs at least 10 mm3, whereas only 6.3% of pasireotide-treated Men1+/− mice (2/32) had pituitary NETs at least 10 mm3 (P < .01, Fisher's exact test)." (PMID 26990064, 2016). "Similarly, in pituitary NETs the mean (±SEM) proliferation rate in pasireotide-treated Men1+/− mice was significantly lower than that in PBS-treated Men1+/− mice (0.73 ± 0.07 vs 1.81 ± 0.15% per day; P < .0001)." (PMID 26990064, 2016). "Similarly, in pituitary NETs the mean (±SEM) apoptosis rate in pasireotide-treated Men1+/− mice was significantly higher than that in PBS-treated Men1+/− mice (14.75 ± 1.58 vs 2.35 ± 0.44%; P < .001)." (PMID 26990064, 2016).
prostate tumour (1 paper, 2025). "MEN1, a known tumour suppressor gene associated with endocrine tumours, was one of the transcriptional regulators most strongly associated with negative TMRs, being the most enriched regulator for negative TMRs identified in both prostate tumour and prostate metastasis samples." (PMID 41036619, 2025).
psychological distress (1 paper, 2019). "The psychological distress and lower health-related quality of life in MEN1-positive individuals also indicate that this topic is highly relevant in everyday clinical practice." (PMID 31044390, 2019).
rectal tumors (1 paper, 2023). "Previous studies have suggested that the MEN1 gene and PI3-K/AKT, Raf/MEK/ERK, Notch, GSK-3β and other signaling pathways may be involved in the occurrence and metastasis of multiple rectal tumors." (PMID 37264328, 2023).
reflux esophagitis (1 paper, 2017). "Heartburn is a typical symptom of reflux esophagitis and is recognized in about 50% of cases of MEN1." (PMID 28270118, 2017).
retinoblastoma (1 paper, 2021). A malignant tumor that originates in the nuclear layer of the retina. "Several studies suggest that oncogenesis in MEN1 individuals involves unmasking of the mutated MEN1 allele at the disease locus by loss of the remaining wild-type copy, in agreement with Knudson’s two-hit mutation model for tumor suppressor genes originally proposed for RB1 loss in retinoblastoma." (PMID 34680266, 2021).
rheumatoid arthritis (1 paper, 2022). A chronic, systemic autoimmune disorder characterized by inflammation in the synovial membranes and articular surfaces. "Preliminary clinical studies in three patients with MEN1 and pNETs have indicated some therapeutic potential of this drug, which has previously been used for some years in patients with rheumatoid arthritis." (PMID 36694894, 2022).
small cell carcinoma (1 paper, 2022). A neuroendocrine carcinoma composed of small malignant cells which are often said to resemble "oat cells" under the microscope. "Previously, only typical and atypical carcinoids, but no LCNEC or small cell carcinoma, have been reported in the setting of MEN1." (PMID 35696052, 2022).
squamous cell carcinoma of the lung (1 paper, 2021). "This included 3 deaths (33%) that were not directly due to MEN1 disease (alcohol, squamous cell carcinoma of the lung, sudden and unknown cause) and one case related to MEN1 but not DP-NETs (thymic carcinoma)." (PMID 33649917, 2021).
teratocarcinoma (1 paper, 2012). A germ cell tumor characterized by the presence of an embryonal carcinoma component and a teratoma component.
Turner syndrome (1 paper, 2017). Turner syndrome is a chromosomal disorder associated with the complete or partial absence of an X chromosome. "Included in this group are four genes commonly associated with Turner syndrome (WNT4, MTHFR, FGFR3, and MEN1)." (PMID 28818098, 2017).
uterine cancer (1 paper, 2025). Primary or metastatic malignant neoplasm involving the uterine corpus and/or the cervix. "The patient with uterine cancer also had FLCN, MEN1 and NF1 PGVs, though none of these three PGVs are typically associated with the uterine carcinoma phenotype either." (PMID 41465149, 2025).
tumor (368 papers, 1999 to 2026). "Many duodenal NETs retain wild-type MEN1 allele and nuclear Menin, suggesting post-translational inactivation of its tumor-suppressor function." (PMID 41993411, 2026). "It is a rare autosomal dominant disorder, resulting from pathogenic inactivating variants in the MEN1 gene, a tumor suppressor located on chromosome 11q13." (PMID 41155355, 2025). "Out of 66 MEN1 patients, 97% (n = 64) had a MEN1 germline mutation, while 3% (n = 2) were diagnosed based on typical tumor manifestations and family history (aggressive = 1, mild = 1)." (PMID 40170567, 2025). "Most glucagonomas are sporadic, rarely they can be inherited: around 3% of inherited glucagonomas can be associated with other tumours in the context of MEN1." (PMID 40613421, 2025). "MEN1 gene testing in an index case can help with early diagnosis and recognition of asymptomatic carriers well before a MEN1-associated tumor can be detected clinically." (PMID 41541958, 2025). "These patients carry germline mutations in the MEN1 gene, and therefore, Menin is considered a tumor suppressor gene in endocrine tissues." (PMID 40374809, 2025). "Our previous study reported that the loss of MEN1 in pNETs can induce a high level of MGMT expression, which impairs the tumor cell response to TMZ via MEN1 deletion mutation-driven activation of the upstream pathway of MGMT." (PMID 41390817, 2025). "Unfortunately, there are still neither clinical nor laboratory markers that reliably indicate an aggressive course of MEN1‐associated NF‐pNET for those patients with a tumor size <2 cm." (PMID 40170567, 2025). "Given the complexity of MEN1 and the risk of significant morbidity from undiagnosed tumors, diagnostic tools and structured screening guidelines are essential for timely tumor detection and effective clinical management." (PMID 40607214, 2025). "In 1993, Knudson suggested that MEN1-related tumors (as well as some other tumor types associated with tumor suppressor genes) require inheritance of a germline mutation along with a somatic mutation in the tumor DNA, leading to LOH." (PMID 41323978, 2025). "MEN1 is caused by germline heterozygous loss-of-function mutations in the MEN1 tumor suppressor gene at locus 11q13, which encodes the oncosuppressor protein menin, whose reduced or totally absent activity is responsible for multiple tumor development." (PMID 40507887, 2025). "The tumor types associated with MEN1 are represented by lactotroph, somatotroph, corticotroph, and nonsecreting adenomas." (PMID 40299639, 2025). "Menin is a scaffold nuclear protein encoded by the MEN1 gene (chromosome 11q13), and it is classically associated with hereditary MEN1 syndrome due to its tumor suppressor role." (PMID 40710017, 2025). "The clinical context, such as family history, or high predictive risk score and demonstration of the variant with biallelic MEN1 loss in the patient’s tumor(s) can help confirm the diagnosis." (PMID 39946193, 2025). "Somatic mutations in MEN1 have been identified in other tumor types but have yet to be shown directly related to carcinoma conversion or to metastatic transformation." (PMID 41293361, 2025). "Approximately 75% of germline MEN1 mutations are truncating variants (nonsense, frameshift, or splice-site mutations), consistent with its tumor suppressor function." (PMID 41323978, 2025). "As a tumor suppressor gene, the frameshift mutations in MEN1 were probable drivers, and the missense mutation was a predicted cancer driver in these canine patients." (PMID 41353477, 2025). "Men1-knockout mice and heterozygous Men1+/− mice on different backgrounds reveal clinical differences, including the risk and outcome of tumor development, which suggests a role for modifier genes." (PMID 38256138, 2024). "Tumor DNA analysis in about 90% of cases shows loss of heterozygosity of the normal MEN1 allele compared to leukocyte DNA." (PMID 39201946, 2024).
tumor (continued). "Such neoplasms are also enriched in MEN1 and ATRX/DAXX mutations and can harbor high-TMB as an actionable target." (PMID 39331358, 2024). "MEN-1 is an autosomal dominant disease resulting from a mutation in the MEN-1 tumour suppressor gene on chromosome 11q13." (PMID 39608104, 2024). "Our results demonstrated that the combined loss of Men1, Atrx, and Pten, tumor suppressors, triggers the initiation and progression of pancreatic neuroendocrine cell tumorigenesis." (PMID 38609433, 2024). "Inhibiting Wnt/β-catenin signaling in Men1-deficient murine β-cells reduces proliferation, and combining a β-cell-specific menin knockout with a β-catenin knockout decreases tumor formation compared to menin knockout alone." (PMID 39336822, 2024). "With respect to MEN1, mutations in or the deletion of the gene have been reported to play a role in pituitary tumorigenesis, with the gene apparently acting as a tumour suppressor." (PMID 39518122, 2024). "Taken together, these data collectively showed that MGMT deficiency upregulated p21 expression and increased tumor cell apoptosis, and these data further suggested that MEN1 is involved in the β‐Catenin‐MGMT signaling cascade in PanNETs." (PMID 39041891, 2024). "MEN1 is an autosomal dominant disorder predisposing to the development of neoplasms, mostly in neuroendocrine tissues." (PMID 37891382, 2024). "Healthy eating and an active lifestyle represent the only modifiable factors that can be implemented to promote personal well-being and ameliorate the quality of life in patients with genetic-caused tumor(s), such as MEN1 patients and MEN1 mutation carriers." (PMID 38892509, 2024). "Family members of patients clinically diagnosed with MEN1 who develop a MEN1-associated tumor meet the criteria for a familial MEN1 diagnosis." (PMID 39371924, 2024). "Secondly, the development of a MEN1-associated tumor in a first-degree relative of an individual already diagnosed with MEN1 serves as another path to diagnosis." (PMID 39201946, 2024). "The familial diagnosis is established when a patient with one MEN1-associated tumor has a first-degree relative with MEN1 and the clinical diagnosis is made if a patient has two or more cardinal MEN1-associated endocrine tumors." (PMID 38893191, 2024). "Univariate and multivariate analysis were performed, but neither outcome—normalization of prolactin levels or tumor size reduction—was significantly associated with factors like sex, age, initial tumor size, treatment duration, or type of germline MEN1 PV." (PMID 39439563, 2024). "It was thought that such c.587delA MEN1 variant and frame-shift variants resulted in aberrant translation of menin, thereby impairing its tumor-suppressing function, and then leading to the occurrence of MEN1." (PMID 39371924, 2024). "Pathogenic variants of MEN1 usually have a truncating effect on menin, with loss of the tumor-suppressing function and an increased risk of developing cancer." (PMID 39371924, 2024). "Despite a clear association between the occurrence of inactivating MEN1 mutations and tumor onset in cases of sporadic and hereditary MEN1 syndrome, knowledge of how these mutations manifest during pathogenesis remains limited." (PMID 37492626, 2023). "A patient tumor with MEN1, BRCA2, PTEN, and SETD2 mutations was passaged in PDX models to create everolimus resistant tumors, followed by treatment with sapaniseritinb, a potent dual mTORC1/2 inhibitor, to overcome resistance." (PMID 37568572, 2023). "In the majority of patients, the tumor formation follows the Knudson’s “two hit model” having one germline mutation in the MEN1 gene while a loss of heterozygosity (LOH) or somatic mutations occurs in the MEN1 alleles of the tumor." (PMID 37109772, 2023). "Autophagy inhibition through chloroquine induced apoptosis in well-differentiated pNEN cell lines via endoplasmic reticulum stress and resulted in decreased tumor size in Men1-heterozygous deficient mice, a mouse model for low-grade pNET." (PMID 36835048, 2023).